HIF1A (hypoxia inducible factor 1 subunit alpha)
Diseases named in the same sentence as HIF1A in open-access papers (continued):
Sharing a sentence is not in itself a finding about the gene and the disease.
nasopharyngeal carcinoma (continued). "In nasopharyngeal carcinoma, the hypoxia-indued lncRNA DLX6-AS1 (long-chain non-coding growth stasis specific protein 6 antisense RNA1) stabilizes HIF-1α mRNA sponging the miR-199a-5p." (PMID 33673376, 2021). "2-Methoxyestradiol (2-ME2) inhibited the HIF-1α expression and reversed the EMT in nasopharyngeal carcinoma." (PMID 33806538, 2021). "In nasopharyngeal carcinoma, EBV-induced angiogenesis mimicry is primarily achieved through the PI3K/AKT/mTOR/HIF-1α/VEGFA signaling cascade." (PMID 32993787, 2020). "In nasopharyngeal carcinoma cells (NPC), both lncRNA PVT1 and lncRNA DANCR can interact with HIF-1α to influence NPC progression." (PMID 33109235, 2020). "Although LMP1 expression was noted in all EBV+ nasopharyngeal carcinomas, there was limited evidence of LMP1 co-localisation with HIF-1α." (PMID 33113858, 2020). "A link between HIF1A expression and smoking/nicotine exposure has been identified in NSCLC and nasopharyngeal carcinoma." (PMID 32894161, 2020). "The bitter melon component α-MMC reduced expression of hypoxia-inducible factor 1-alpha (HIF1α) and vascular endothelial growth factor (VEGF) in hypoxic nasopharyngeal carcinoma cells, and inhibited growth of human umbilical vein endothelial cells." (PMID 32726914, 2020). "In addition, we have shown that HIF-1α can be transferred with nasopharyngeal carcinoma-associated LMP1-positive exosomes, and that such transcriptionally active HIF-1α supports the invasive potential of NPC." (PMID 31370144, 2019). "Nasopharyngeal carcinoma patients with low FoxO3a and high Hypoxia-inducible factor 1α (HIF-1α) expression had poorer prognosis than patients with high FoxO3a and low HIF-1α levels." (PMID 26405162, 2015). "This study investigates the expression of hypoxia-inducible factor-l alpha (HIF-1α) and carbonic anhydrase IX (CAIX) in nasopharyngeal carcinoma (NPC) tissues and their correlation with clinicopathological features and prognosis in NPC patients." (PMID 25377659, 2014). "In nasopharyngeal cancer, lncRNA PVT1 can act as a scaffold for the chromatin modifier KAT2A, recruiting the nuclear receptor-binding protein TIF1β to activate NF90 transcription, thereby increasing HIF-1α and upregulating radioresistance." (PMID 35600868, 2022). "Moreover, HIF-1α and VEGF inhibitors can effectively inhibit vasculogenic mimicry in nasopharyngeal carcinoma." (PMID 32993787, 2020). "DANCR could stabilize HIF-1α mRNA through interacting with NF90/NF45 complex, leading to nasopharyngeal carcinoma metastasis and invasion." (PMID 33123287, 2020). "The analysis revealed HIF-1α overexpression significantly correlated with worse survival outcomes in oral carcinoma, nasopharyngeal carcinoma and oropharynx carcinoma, but not in laryngeal cancer." (PMID 30840126, 2019). "In nasopharyngeal carcinoma, TFAP2A regulated tumor cell growth and survival through the HIF-1α-mediated VEGF/PEDF signaling pathway, suggesting that TFAP2A could be a potential biomarker for nasopharyngeal carcinoma treatment." (PMID 25860484, 2015). "Since areca, an oral carcinogen, up-regulates HIF1α in HNSCC cells and nicotine is also known to markedly up-regulated HIF1α expression in nasopharyngeal carcinoma cells, it seems likely that miR-372 contributes to human HNSCC genesis via stimulation by habitual use of carcinogenic substances." (PMID 25714028, 2015). "Of note, the observation of HIF-1α protein reduction corroborated the hypothesis of a deregulation of hypoxia signaling by PVT1, which has been already demonstrated to have a key role in HIF-1α stabilization in nasopharyngeal carcinoma." (PMID 39922814, 2025). "miR-144, enriched in tumor-derived extracellular vesicles (EVs) from nasopharyngeal carcinoma (NPC), is demonstrated in vitro and in vivo to promote angiogenesis by downregulating FBXW7 and promoting HIF-1α-induced VEGF-A expression." (PMID 35515121, 2022).
nasopharyngeal carcinoma (continued). "TH-302 decreased proliferation and HIF-1α expression in acute myeloid leukemia (AML) and nasopharyngeal carcinoma (NPC) cells and induced cell-cycle arrest, and enhanced double-stranded DNA breaks." (PMID 33953675, 2021). "Specifically, LMP1 was shown to enhance the synthesis of HIF-1α and the expression of HIF-1α-responsive genes in a nasopharyngeal carcinoma (NPC)-derived cell line, which could be attributed to enhanced degradation of prolylhydroxylases (PHD) 1 and 3 mediated by SIAH1." (PMID 30395643, 2018). "As an example, differentiation antagonizing non-protein coding RNA (DANCR) increases HIF-1α mRNA stability and promotes nasopharyngeal carcinoma (NPC) cell invasion and metastasis." (PMID 32550915, 2020).
oral cancer (66 papers, 2005 to 2026). "HIFCAR can engage HIF-1α and P300 to form a transcriptional complex that promotes target gene transcription and tumor growth by directly binding to the promoter region of HIF-1α target genes in oral cancer." (PMID 41614928, 2026). "Specifically, SAB has been shown to regulate glycolysis through the PI3K/AKT/HIF-1α signaling pathway, thereby inhibiting metabolic reprogramming and tumor growth in a hamster oral cancer model." (PMID 41439141, 2025). "Previous studies have shown that IL-17F suppresses VM in oral tongue squamous cell carcinoma; HIF-1α/EphA2/Laminin-5γ2 axis downregulation inhibits hypoxia-induced VM in oral cancer; SOX7 inhibits VM by downregulating VE-cadherin in OSCC." (PMID 41502523, 2025). "Studies have also demonstrated that SAB inhibits HIF-1α and VEGF expression, thereby suppressing tumor-associated neovascularization in oral cancer cell lines." (PMID 41439141, 2025). "Exhibits dose- and time-dependent antiproliferative and pro-apoptotic effects through mitochondria/death receptor, MAPK, NF-κB, and HIF-1α signaling pathways; potential candidate for oral cancer chemotherapy." (PMID 39518052, 2024). "We have previously shown that HIF-1α is highly expressed in YD-38 human oral cancer cells, and its expression is crucial for their survival." (PMID 38474118, 2024). "Some other adjuvants such as metformin and glucosamine have been shown to increase apoptosis in oral cancer cells and sensitize these cells to chemotherapy by inhibiting HIF-1α." (PMID 37221555, 2023). "Next, we examined HIF-1α expression in three oral cancer cell lines: HSC-2 (metastatic site), SCC-9 (tongue), and SCC-25 (tongue)." (PMID 37095487, 2023). "Some experiments have been conducted to sensitize oral cancer cells to radiation or drugs by inhibiting HIF-1α." (PMID 37221555, 2023). "MIR31HG then interacts with HIF-1α itself, favoring its recruitment on target promoters involved in oral cancer progression." (PMID 35456025, 2022). "Recent studies have shown that areca nuts and arecoline can induce HIF-1α expression in oral fibroblasts and oral cancer cells." (PMID 36429032, 2022). "At present, the mechanisms underlying high HIF‐1α protein expression and dasatinib regulation of HIF‐1α expression in oral cancer cells are poorly understood." (PMID 34318593, 2021). "VEGF overexpression is closely related to advanced disease and poor survival in in vitro experiments and bioinformatics, revealing a novel HDGF/HIF-1α/VEGF axis in oral cancer prognosis." (PMID 34322156, 2021). "In the group of G2 tumours (Ki-67 40–70%), differences in the expression of examined proteins reached medial values: the mean value of PRODH/POX expression in oral cancer tissue was 55%, the mean value of PPARy—60% and mean value of HIF-1α—137%." (PMID 31935820, 2020). "Our data have shown that exogenous HDGF protein not only stimulated the phosphorylation levels of AKT and IκB but also increased the protein levels of the transcriptional factors HIF-1α and NF-κB p65 in oral cancer cells." (PMID 31711427, 2019). "In another study, it was also reported that HDAC2 expression led to invasion/migration of human oral cancer cell lines via HIF-1α stability regulation." (PMID 30135512, 2018). "Further, we provide evidence to demonstrate that nimbolide activates RECK by inhibiting miR-21 and HIF-1α under hypoxic conditions in a cellular context using the oral cancer cell lines SCC131, SCC4 and the endothelial cell line EAhy926." (PMID 28515436, 2017). "In oral carcinoma and oral cancer cell lines, melatonin inhibited the expression of the proangiogenic factors, HIF1α and VEGF revealing an effect of melatonin on inhibition of angiogenic responses in oral cancer." (PMID 29163852, 2017). "Hif-1α is known to play an important role in the pathogenesis of oral cancer and functions an independent prognostic marker of oral SCC." (PMID 25050571, 2014).
oral cancer (continued). "Contradictory results relating to the role of HIF-1α in oral carcinomas have also been reported, however." (PMID 23599780, 2013). "There is a growing body of evidence suggesting that HIF-1α is involved in the progression of oral cancers." (PMID 23599780, 2013). "Alteration and over-expression of HIF-1α has been detected in a variety of solid tumors, including breast, lung, ovarian and oral cancer." (PMID 21726465, 2011). "We also investigated the CYGB and HIF1A response of human oral cancer cell lines to hypoxic conditions." (PMID 19568272, 2009). "Alteration and overexpression of HIF-1α has been detected in a variety of solid tumours, including breast, lung, ovarian and oral cancer with varying (diffuse and perinecrotic) staining patterns." (PMID 16035955, 2005). "In contrast, MIR31HG acts as an HIF-1α co-activator and drives oral cancer progression." (PMID 35743003, 2022). "Also, MIR31HG expression has been investigated and found increased in HNSCCs and oral cancers, where it has been reported as a lncRNA induced by HIF-1α." (PMID 35456025, 2022). "LncRNA HIFCAR/MIR31HG was found to be a HIF-1α co-activator that promoted oral cancer progression." (PMID 34012919, 2021). "Overexpression of HIF-1α occurs early in the development of oral cancer." (PMID 33466636, 2021). "In this study, we found high HIF‐1α protein expression in all four human oral cancer cell lines." (PMID 34318593, 2021). "The results of our study demonstrated lower expression of PRODH/POX and PPARγ and higher expression of HIF-1α in oral cancer tissue in comparison to normal tissue in all study participants, although the obtained values differed significantly between individual patients." (PMID 31935820, 2020). "Therefore, the HDGF/nucleolin/HIF-1α/VEGF axis is a very attractive target for oral cancer treatment." (PMID 31711427, 2019). "In oral cancer cells, treatment of areca nut extract may induce ROS generation and up-regulate HIF-1α, which may further lead to autophagy to benefit cell survival." (PMID 31417650, 2019). "Melatonin also inhibits HIF-1α expression in oral cancer cells." (PMID 29725496, 2018). "Our results also indicate that targeting miR-21 and HIF-1α with phytochemicals such as nimbolide may be a robust therapeutic approach to modulate multiple proteins and pathways deregulated in oral cancer." (PMID 28515436, 2017). "Collectively, these data provide the first evidence of antiproliferative and apoptosis-inducing effects of IK as a HIF-1α inhibitor and suggest it may be a drug candidate for chemotherapy against oral cancer." (PMID 25105148, 2014). "The correlation between HIF-1α expression and oral cancers has been widely reported." (PMID 23599780, 2013). "Consumption of tobacco may significantly induce the expression of nuclear hypoxia-inducible factor (HIF)-1α, which is an unfavorable prognostic factor in oral cancer." (PMID 23226559, 2012). "Therefore, HIF-1α expression in early stage oral carcinomas was evaluated in relation to established clinico-pathological features in order to determine its value as a prognostic marker." (PMID 16035955, 2005). "Therefore, inhibition of HIF-1α can be suggested for reducing oral cancer resistance to therapy." (PMID 37221555, 2023). "The expression of hypoxia-inducible factor 1-alpha (HIF-1α), a protein central to controlling hypoxic tumor microenvironments, has been reported to be higher in tumor specimens obtained from patients affected by oral cancer who endorse alcohol consumption than those who deny it." (PMID 33668576, 2021). "The prognostic relevance of hypoxia in oral cancer has already been reported by other studies before, mostly using immunohistochemical staining for hypoxia biomarker such as hypoxia-inducible factor 1-alpha (HIF1a) and glucose transporter 1 (GLUT1 or other proteins such as CD44)." (PMID 32984043, 2020).
oral cancer (continued). "Thus, an increase in HIF-1α expression may influence oral cancer progression by promoting tumor angiogenesis and by direct stimulation of tumor cell growth." (PMID 24137322, 2013). "Among these, HIF1α, CDH1, CD44, EGFR, and CCND1 were identified as the top hub genes that have also been reported as driver candidates responsible for oral cancer initiation and progression." (PMID 37316916, 2023). "Hypoxia related genes NF-κB, HIF1α, HK2, and PFKL were upregulated in CAFs activated by oral cancer-derived EVs." (PMID 37745296, 2023). "In oral cancer, HDGF has been observed to induce VEGF gene expression by upregulating HIF-1α and NF-κB." (PMID 34782720, 2022). "LncHIFCAR (long noncoding HIF-1α co-activating RNA) was also found to act as a HIF-1α co-activator which promoted HIF-1α activation and oral cancer progression." (PMID 35006436, 2020). "In a study in oral cancer, MIR31HG was identified as a hypoxia-inducible lncRNA and forms a complex with hypoxia-inducible factor-1 α (HIF-1α), thus as an adverse prognostic predictor for the cancer progression." (PMID 33334367, 2020). "For example, Wei and coworkers demonstrated a general downregulation of HIF-1α and phosphatidylinositol-4-5-bisphosphonate 3 kinase (PI3K) by salvianolic acid B in an experimental oral cancer model." (PMID 32846951, 2020). "Together, these results implied that HDGF stimulated AKT/HIF-1α/NF-κB signaling, thereby modulating VEGF expression in oral cancer cells." (PMID 31711427, 2019). "Treatment with ERK inhibitor U0126 and Akt inhibitor LY294002 significantly reduced the levels of HIF-1α and VEGF, suggesting that the upregulation of HIF-1α and VEGF is partly dependent on ERK and Akt activation in oral cancer cells." (PMID 29725496, 2018). "In this study, we demonstrated that the phosphorylation of ERK and Akt and the expression of HIF-1α and VEGF were highly elevated in oral cancer cells in vitro and in vivo." (PMID 29725496, 2018). "In human oral cancer, A2BAR was shown to be upregulated in oral squamous carcinoma cells, and A2BAR knockdown reduced the proliferation of oral cancer cells through HIF-1α activation." (PMID 27606311, 2016). "Notably, HIF1A and EGLN3 mRNA levels show an upregulation in metastatic HNSCC cell lines when compared to cell lines originating from oral cancer." (PMID 38928200, 2024). "Furthermore, HDGF binds to membrane NCL to activate the HIF-1α/VEGF axis, and Akt/NFκB signaling contributes to poor disease control in oral cancer." (PMID 37827291, 2023). "Further, higher expression of CTSC, HIF1A, and IL1B was observed in both stages of oral cancer." (PMID 38234400, 2023). "Thus, 6,8-DG stimulates the proteasome degradation of HIF-1α in cancer cells, thereby inhibiting the expression of VEGF-A, a major lymphangiogenic factor in oral cancer." (PMID 33466636, 2021). "Arecoline, a major areca nut alkaloid might induce significantly increases expressions of β-catenin, Hypoxia inducible factor (HIF)-1α and Heat shock protein 70 (HSP70) in oral cancer." (PMID 28404909, 2017). "In addition, MIR31HG could recruit HIF-1α and its cofactors to targets genes and activate the HIF-1 transcriptional network in oral carcinoma." (PMID 37950038, 2024).
endometrial cancer (64 papers, 2006 to 2026). Primary or metastatic malignant neoplasm involving the endometrium (mucous membrane that lines the endometrial cavity). "In this study, the histological grade of endometrial cancer exhibited a significant association with HIF-1α expression." (PMID 39202223, 2024). "In our study, drug signatures of Emetine and Cephaeline, known to inhibit HIF1A, were negatively associated with the tumor necrosis signature, further supporting hypoxia as an important feature of aggressive endometrial cancer." (PMID 26485755, 2015). "Studies have determined that transcriptional associations with HIF-1α, NF-κB, and β-catenin/p300 complexes contribute to hypoxic condition-changed tumor cell kinetics in endometrial carcinomas." (PMID 26593914, 2015). "In endometrial cancer, low ascorbate levels are associated with high hypoxia-inducible factor-1α (HIF-1α) activation, HIF-1α-mediated up-regulation of glucose transporter 1 (GLUT-1) and an aggressive tumour phenotype." (PMID 24330097, 2014). "Research also shows that vitamin C presents a potential role in the regulation of HIF-1α activity and its supplementation might reduce the risk of endometrial cancer development." (PMID 39337406, 2024). "These lncRNA-mRNA-miRNA regulatory associations have been observed in many diseases, including endometrial cancer; lncRNA H19, for example, was reported to accelerate tumor formation in endometrial cancer by regulating HIF-1α/AXL signaling through competition for miR-20b-5p." (PMID 33584822, 2021). "In stage 1 endometrial cancers, HIF-1α was associated with a worse prognosis." (PMID 20169098, 2010). "Interestingly we found that the P582S genotype variation in the ODDD of the HIF-1α protein may occur as a de novo mutation in endometrial cancer." (PMID 20169098, 2010). "Other studies have shown that inactivation of JAK1 promotes proliferation of endometrial cancer cells by upregulating the HIF1α signaling pathway." (PMID 41520505, 2026). "In endometrial cancer, HIF-1α promotes apoptosis by facilitating MST2 cleavage and activating the Caspase pathway." (PMID 41256331, 2025). "High expression of HIF-1α contributes to high aggressiveness or poor prognosis of endometrial cancer." (PMID 40444079, 2025). "Analysis of histological grade and HIF-1α expression in ICs using a 1% threshold for HIF-1α expression revealed that grades 2 and 3 endometrial cancer exhibited significantly higher expression levels than 1% (p < 0.05)." (PMID 39202223, 2024). "The hypoxic markers, HIF-1α and GLUT-1, are associated with poor prognosis in endometrial cancer, although there are slight variations in specific parameters." (PMID 39202223, 2024). "In endometrial cancer (EC), miR-320a inhibits the proliferation of EC cells, downregulates the expression of hypoxia-inducible factor 1 alpha (HIF-1α) in EC cells, and inhibits HIF1α/VEGFA axis." (PMID 37168385, 2023). "The classical nuclear transcription factor NF-kB pathway is thought to be activated in endometrial cancer cells via HIF-1α." (PMID 36611913, 2022). "Another group discovered that miR-320a in extracellular vesicles (EVs) distorts endometrial cancer by disrupting the HIF1α/VEGFA signaling pathway." (PMID 35201481, 2021). "Endometrial cancer biopsies from women treated with pre-surgical metformin were tested for the hypoxia markers, HIF-1α and CA-9." (PMID 31819173, 2020). "Endometrial cancer patients with higher HIF-1α protein expression had poorer prognosis compared to patients with low HIF-1α protein expression (HR = 2.29, 95% CI = 1.68-2.90, P < 0.05)." (PMID 33304847, 2020). "Information including HIF-1α protein expression and clinical progression of endometrial cancer was extracted." (PMID 33304847, 2020). "HIF-1α protein expression in endometrial cancer tissue was significantly higher than that in normal tissues (OR = 15.79, 95% CI = 8.44-29.52, P < 0.05)." (PMID 33304847, 2020).